CT83 (cancer/testis antigen 83)
Synonyms: KK-LC-1; CXorf61; KKLC1; FLJ20611; FLJ22913
Tractability: Antibody: UniProt places it where antibodies can reach, with high confidence; UniProt predicts a signal peptide or a membrane-spanning region; its Gene Ontology location is reachable by antibodies, with medium confidence. PROTAC: ubiquitination databases record sites on it.
Gene: Protein-coding gene on chromosome X (116,461,686 to 116,462,976, reverse strand). Ensembl gene ENSG00000204019.
Subcellular location: Cell membrane
Gene Ontology:
Cellular component: nucleus; plasma membrane
Homologues: Orthologues: chimpanzee CT83 (100% identical), macaque CT83 (89% identical), dog CT83 (61% identical), pig CT83 (61% identical).
Diseases named in the same sentence as CT83 in open-access papers:
CT83 is named in the same sentence as 45 diseases in open-access papers, as found by Europe PMC text mining. Sharing a sentence is not in itself a finding about the gene and the disease. The quoted sentences say what the papers report.
breast carcinoma (19 papers, 2015 to 2025). "Hypomethylation is probably one of the causes of the abnormal activation of CT83 in breast cancer." (PMID 34108519, 2021). "In addition, we also assessed the correlation between CT83 mRNA expression levels and mutations of key genes in breast cancer." (PMID 34108519, 2021). "Here, we describe the preclinical characterization of a TCR directed against Kita-Kyushu Lung Cancer Antigen-1 (KK-LC-1, encoded by CT83), a cancer germline antigen with frequent expression in human epithelial malignancies including gastric cancer, breast cancer, and lung cancer." (PMID 31455429, 2019). "In total, these results illuminate the potential for HORMAD1 and CT83 use as biomarkers for basal-like breast cancers by showing both their specificity for the subtype as well as the functional consequences of their co-activation." (PMID 38467851, 2024). "Among the included 2971 breast cancer tissue samples, CT83 amplification rate was only less than 1% in both datasets." (PMID 34108519, 2021). "According to data from the TCGA-BRCA and the METABRIC dataset, copy number variation (amplification and deep deletion) of CT83 is a rare event in breast cancer tissues." (PMID 34108519, 2021). "Searching Pubmed with keywords “CT83” and its commonly used synonyms like “CXorf61” and “KK-LC-1,” there were only about 20 studies available regarding CT83 in cancer, mostly in breast cancer, lung cancer, gastric cancer, and hepatocellular cancer." (PMID 34108519, 2021). "In brief, high CT83 mRNA expression is usually unfavorably prognostic for OS in breast cancer, and correlated with worse RFS and OS in KIRP, LIHC, LUAD, and THYM." (PMID 34108519, 2021). "Regarding CT83 in breast cancer, several studies have identified and emphasized its TNBC specificity but with a limited sample size." (PMID 34108519, 2021). "Conversely, the abnormal activation of CT83 is often detected in cancer tissues including breast cancer, and its high expression is statistically different from paired normal tissues in lung adenocarcinoma (LUAD) and stomach adenocarcinoma (STAD) tissues." (PMID 34108519, 2021). "Apart from breast cancer, copy number variation of CT83 is also uncommon in pan-cancer tissues and cell lines." (PMID 34108519, 2021). "Next, we investigated the RNA-seq and microarray data from the TCGA-BRCA, METABRIC, FUSCC-TNBC, and CCLE-BRCA dataset to get a better understanding of the expression CT83 mRNA in breast cancer tissues and cell lines." (PMID 34108519, 2021). "To assess the frequency of cells within a tumor that express CT83, we performed RNA in situ hybridization with RNAScope on gastric cancers, breast cancers, and lung cancers." (PMID 31455429, 2019). "Triple negative breast cancer also had varying frequencies of expression, with 4/9 samples positive for CT83." (PMID 31455429, 2019). "The biological role of CT83 in breast cancer is currently poorly understood." (PMID 34108519, 2021). "Overexpression of CT83 in breast cancer may be oncogenic by triggering the activation of signaling associated with the cell cycle." (PMID 34108519, 2021). "Meanwhile, we predicted that the hypomethylation of the region 116,463,019 to 116,463,039 on chromosome X may induce the abnormal activation of CT83 in breast cancer." (PMID 34108519, 2021). "Taken together, these data indicated that the aberrant activation of CT83 may interact with one or more of the 16 cell cycle correlated genes to promote tumorigenesis in breast cancer." (PMID 34108519, 2021). "Therefore, we analyzed the correlation between CT83 mRNA expression levels and its methylation status in breast cancer tissues with the TCGA-BRCA dataset." (PMID 34108519, 2021). "Similarly, data from TCGA-BRCA suggested that CNVs and mutations of CT83 in breast cancer or pan-cancer are quite rare, thus the two areas should not be the research priority in future studies." (PMID 34108519, 2021).
breast carcinoma (continued). "Kita-Kyushu Lung Cancer Antigen-1 (KK-LC-1, encoded by CT83) is a cancer germline (CG) antigen that is reported to have restricted expression in healthy tissues and frequent expression in certain epithelial cancers including lung cancer, gastric cancer, and breast cancer." (PMID 31455429, 2019). "In breast cancer cell lines as well, 70% of basal-like cell lines from CCLE were positive for HORMAD1 or CT83 and 35% for both." (PMID 38467851, 2024). "To observe dynamic cell killing, we performed a real-time cytotoxicity assay for CT83/TCR1-Ts against three representative CT83/A11-positive cell lines from stomach, lung, and breast cancers." (PMID 35798537, 2022). "CT83 is a gene specific to TNBC and its hypermethylation is oncogenic in breast cancer." (PMID 38435998, 2024). "Moreover, the high expression of CT83 mRNA, defined as 10 TPM or more, is also often detected in cancer cell lines, especially in cell lines of breast cancer, liver cancer, lung cancer, pancreas cancer, and stomach cancer." (PMID 34108519, 2021). "Briefly, data from 672 TNBC tissues, 2184 non-TNBC breast cancer tissues, 17 TNBC cell lines, and 35 non-TNBC breast cancer cell lines demonstrated that CT83 is distinctively and frequently overexpressed in TNBC." (PMID 34108519, 2021). "Moreover, the positive rate of CT83 mRNA is the highest in either TNBC tissues or cell lines, while its expression is always undetectable in breast cancer tissues or cell lines of other subtypes." (PMID 34108519, 2021). "Similarly, CT83 amplification was detected in 6/51 of the CCLE-BRCA cell lines, while its deep deletion was observed in only 2 breast cancer cell lines." (PMID 34108519, 2021). "As mentioned in the screening part, the expression of CT83 mRNA is significantly higher in Basal/TNBC tissues compared with other subtypes, and a similar trend was observed in the 57 breast cancer cell lines (including 17 TNBC cell lines) in which the expression of CT83 mRNA was measured." (PMID 34108519, 2021). "CT83 is not prognostic in breast cancer but is valuable for the prognosis prediction in KIRP, LIHC, and LUAD." (PMID 34108519, 2021). "In this study, from over 60,000 genes and 3617 breast cancer samples, we identified a TNBC-specific key gene, CT83, which is significantly overexpressed in TNBC but not in other breast cancer subtypes." (PMID 34108519, 2021). "Like CT83, also Actin like 8 (ACTL8) is already described as a potential target in breast cancer and is, to our knowledge, absent from current immunotherapy development as well." (PMID 31069014, 2019).
lung carcinoma (16 papers, 2015 to 2025). "Kita-Kyushu lung cancer antigen 1 (KK-LC1), encoded by cancer/testis antigen 83 (CT83), is a single-pass membrane protein normally expressed in testis, and other cancer types including lung cancer." (PMID 34048178, 2021).
gastric cancer (14 papers, 2018 to 2025). A primary or metastatic malignant neoplasm involving the stomach. "CT83 was however expressed by a range of epithelial cancers, with the highest expression noted in gastric cancer." (PMID 31455429, 2019). "Gastric cancers commonly demonstrated CT83 expression, and a high fraction of cell expressed the antigen in some tumors (5/9 tumors examined showed at least 50% positivity)." (PMID 31455429, 2019). "The highest frequency of positive cells occurred in gastric cancers, of the 13 samples tested, 9 were positive for CT83 expression (median: 50%, range: 5 to 90%)." (PMID 31455429, 2019). "In gastric cancer, CT83 is also frequently overexpressed and related to poor outcomes." (PMID 34108519, 2021). "CT83, also known as KK-LC-1, is one such CTA reported to be highly expressed in various cancers, such as gastric cancer, triple-negative breast cancer, lung adenocarcinoma, and cervix cancer." (PMID 40141328, 2025). "Our previous study demonstrated frequent CT83 expression in gastric cancers (GCs) and non-tumor sites of the stomach with tumors." (PMID 36484013, 2022). "Pylori IgG titers from the CT83‐positive gastric cancer patients were significantly higher (67.5 ± 7.6) than those from CT83‐negative gastric cancer patients (15.8 ± 7.5)." (PMID 29856138, 2018).
triple-negative breast carcinoma (10 papers, 2015 to 2025). An invasive breast carcinoma which is negative for expression of estrogen receptor (ER), progesterone receptor (PR), and human epidermal growth factor receptor 2 (HER2). "To further corroborate this apparent synergistic effect of HORMAD1 and CT83 expression, we performed loss-of-function experiments in a triple-negative breast cancer line that endogenously expresses both genes, MDA-MB-436." (PMID 38467851, 2024). "Using the histological classification of breast tumors, we found the same result: HORMAD1 and CT83 are the two best predictors of triple-negative breast cancers within C/T genes." (PMID 38467851, 2024). "In the absence of treatment, we validated by RT-qPCR that these cell lines do not express HORMAD1 and CT83, in contrast to the triple-negative breast cancer line MDA-MB436." (PMID 38467851, 2024).
lung adenocarcinoma (6 papers, 2016 to 2025). A carcinoma that arises from the lung and is characterized by the presence of malignant glandular epithelial cells. "In pan-cancer analysis, CT83 high expression is correlated with worse RFS in kidney renal papillary cell carcinoma (KIRP), liver hepatocellular carcinoma (LIHC), and lung adenocarcinoma (LUAD)." (PMID 34108519, 2021).
cervical cancer (5 papers, 2018 to 2025). A primary or metastatic malignant neoplasm involving the cervix. "CT83 expression was analyzed in cervical cancer cell lines using quantitative PCR and Western blotting." (PMID 40141328, 2025). "The findings from our study emphasize the need for the further exploration of CT83 as a therapeutic target in cervical cancer." (PMID 40141328, 2025). "Our study provides compelling evidence that CT83 expression is significantly elevated in cervical cancer cell lines and tissues." (PMID 40141328, 2025). "We previously observed CT83 expression in a human papillomavirus (HPV) + metastatic cervical cancer." (PMID 31455429, 2019). "Moreover, the infusion of CT83-specific T-cell receptor (TCR) gene-engineered T cells (TIL) resulted in the complete regression of metastatic cervical cancer." (PMID 40141328, 2025). "While these findings highlight the significance of CT83 in cervical adenocarcinoma progression, further studies are needed to determine whether similar patterns are observed in other cervical cancer subtypes." (PMID 40141328, 2025). "Functional assays demonstrated that CT83 overexpression (OE) promotes proliferation, migration, invasion, and epithelial–mesenchymal transition (EMT) in cervical cancer cells while also upregulating PD-L1 expression." (PMID 40141328, 2025). "A study on the immunotherapy of virally induced epithelial cancer revealed that CT83 is expressed in metastatic cervical cancer tissue but not in normal tissue." (PMID 40141328, 2025).
melanoma (2 papers, 2018 to 2019). A malignant, usually aggressive tumor composed of atypical, neoplastic melanocytes. "Lung, breast, cervical, ovarian, melanoma, prostate, and leukemia cancer cell lines were found to express CT83, albeit with varying levels and frequencies of expression." (PMID 31455429, 2019).
breast tumors (1 paper, 2024). "These bioinformatic analyses provide clear evidence that, of the various C/T genes identified, HORMAD1 and CT83 are the most compelling as potential biomarkers for basal-like breast tumors due to their basal tumor-specific expression." (PMID 38467851, 2024). "To begin uncovering the role of HORMAD1 and CT83 expression in basal-like breast tumors, we first wanted to understand how this aberrant expression becomes induced." (PMID 38467851, 2024). "The two best predictors, HORMAD1 and CT83, are strongly associated with basal breast tumors: of the 190 basal-like breast tumors, 89% expressed either HORMAD1 or CT83, compared to only 13% of Her2-amplified, 6% of Luminal B, and 2% of Luminal A tumors." (PMID 38467851, 2024). "We then use machine learning to identify the two Cancer/Testis genes most associated with basal-like breast tumors: HORMAD1 and CT83." (PMID 38467851, 2024). "We then focus on the two genes whose expression is most highly associated with basal breast tumors: HORMAD1 and CT83." (PMID 38467851, 2024). "These promoters overlap the ATAC-seq peaks which are present in HORMAD1/CT83-expressing basal-like breast tumors, but absent in non-expressing tumors." (PMID 38467851, 2024).
cervical adenocarcinoma (1 paper, 2025). An adenocarcinoma arising from the cervical epithelium. "As a highly expressed antigen in cervical adenocarcinoma, CT83 offers promise as a diagnostic marker and therapeutic target for improving patient outcomes." (PMID 40141328, 2025). "In this study, we aimed to evaluate CT83 expression and its role in tumor progression and prognosis in cervical adenocarcinoma." (PMID 40141328, 2025). "Western blot revealed that CT83 was highly expressed in the HeLa (adenocarcinoma of the cervix) and KATO (control) cell lines." (PMID 40141328, 2025). "Immunohistochemistry showed CT83 positivity in 84.9% of cervical adenocarcinoma samples, correlating with a larger tumor size (p = 0.046), and elevated SCC levels (p = 0.037)." (PMID 40141328, 2025). "Nevertheless, our study underscores CT83 as a potential biomarker in cervical adenocarcinoma, providing a new focus for research and therapeutic targeting." (PMID 40141328, 2025). "CT83 is highly expressed in cervical adenocarcinoma cell lines and tissues, with lower expression in cervical squamous carcinoma cell lines." (PMID 40141328, 2025). "CT83 may serve as a potential biomarker and therapeutic target, specifically in cervical adenocarcinoma." (PMID 40141328, 2025). "Notably, CT83 demonstrated the highest expression levels in cervical adenocarcinoma, which was corroborated by the IHC staining of patient tissues." (PMID 40141328, 2025). "Additionally, we assessed the correlation between clinical factors and CT83 expression in women with cervical adenocarcinoma." (PMID 40141328, 2025). "CT83 plays a role in immune evasion by modulating PD-L1 and could serve as a biomarker and therapeutic target for cervical adenocarcinoma." (PMID 40141328, 2025).
gastric atrophy (1 paper, 2022). "Conversely, among non-GC patients with gastric atrophy, we identified 8 of 115 (7.0%) with CT83 expression." (PMID 36484013, 2022).
myeloma (1 paper, 2018). "In the current study, monoclonal antibodies against human CT83 were developed by fusing solenocytes from immunized mouse with SP2/0 myeloma cells and polyethylene glycol." (PMID 29856138, 2018).
cancer (26 papers, 2015 to 2025). A tumor composed of atypical neoplastic, often pleomorphic cells that invade other tissues. "Using Kaplan–Meier Plotter, we demonstrated that activated CT83 is significantly associated with unfavorably overall survival in BrC and worse outcomes in some other cancers." (PMID 34108519, 2021). "In 8176 TCGA pan-cancer tissues spanning 33 cancer types, mutated CT83 was only detected in 15 samples." (PMID 34108519, 2021). "Similarly, among the 1574 CCLE pan-cancer cell lines, CT83 mutations were only observed in 8 cell lines of 7 mixed cancer types." (PMID 34108519, 2021). "The relationship between PD-L1 (Programmed Death-Ligand 1) and CT83 in cancer is an emerging area of interest, primarily due to the roles these proteins play in immune evasion and tumor progression." (PMID 40141328, 2025). "Our results suggest that CT83 promotes cancer metastasis, invasion, and potentially contributes to increased apoptosis by facilitating EMT." (PMID 40141328, 2025). "CT83, a cancer-testis antigen, has emerged as a potential biomarker and therapeutic target in various cancers." (PMID 40141328, 2025). "Recently, T-cell receptor (TCR) gene-engineered T cells targeting CT83 have been developed as a new treatment strategy for various cancers." (PMID 40141328, 2025). "While many Cancer/Testis genes are repressed by DNA methylation, HORMAD1 and CT83 are highly specific in their association with basal tumors." (PMID 38467851, 2024). "Within any given tumor approximately 20–40% of individual cancer cells express either HORMAD1 or CT83, and around 5–20% express both." (PMID 38467851, 2024). "A GSEA analysis revealed that the “HORMAD1 + CT83” signature detected in HMLE cells was significantly correlated to the transcriptome profile of double-positive cancer cell lines and with the transcriptome of double-positive tumors." (PMID 38467851, 2024). "CELSR3 is expressed in Epithelial Cells, CT83 is highly expressed in Cancer cells, Epithelial cells, and Neutrophils, and CXCL11 is expressed in Fibroblast and M1 Macrophages." (PMID 37985782, 2023). "To investigate the potential of CT83/TCR1-Ts to mediate the regression of cancers in vivo, we employed immunodeficient NCG mice to establish murine CDX models." (PMID 35798537, 2022). "Why was it easier to isolate high-avidity TCRs from healthy individuals or patients with cancer against CT83 in these three studies?" (PMID 35798537, 2022). "This evidence indicates that CT83/TCR1 specifically recognizes cancer cell lines from three common solid cancers: stomach, breast, and lung." (PMID 35798537, 2022). "Briefly, our data not only highlighted the importance of CT83 for TNBC but also presented a comprehensive bioinformatics strategy for the analysis of cancer-related genes." (PMID 34108519, 2021). "These expression patterns of CT83 are consistent with previous understanding about typical cancer/testis antigens, indicating that CT83 is a potential therapeutic target in cancer immunotherapy." (PMID 34108519, 2021). "Specifically, CT83 amplification was detected in 14/923 (1.52%) cancer cell lines based on CCLE pan-cancer CNV data." (PMID 34108519, 2021). "In 33 types of TCGA cancer tissues, most of the detected CT83 DNA were diploid, while its DNA amplification or deep deletion was still rare events." (PMID 34108519, 2021). "Of the identified, cancer-specific antigens in our list, the cancer/testis antigen 83 (CT83) had the most interesting profiles with high expression in more than 65% of triple-negative tumor samples and lower expression in almost all normal tissues examined." (PMID 31069014, 2019). "Then the antibodies were screened with prokaryotic expressed human CT83 protein and the endogenous CT83 protein of the cancer cell lines subsequently." (PMID 29856138, 2018). "The knockdown of CT83 reduces cancer cell aggressiveness and PD-L1 expression." (PMID 40141328, 2025).